BRCA1 (BRCA1 DNA repair associated)
Diseases named in the same sentence as BRCA1 in open-access papers (continued):
Sharing a sentence is not in itself a finding about the gene and the disease.
cancer (continued). "As for biomarkers, alternative transcripts of the BRCA1 gene in patients with BrCa and a family history of breast/ovarian cancer revealed the presence of three prevalent isoforms in blood samples that were probably pathogenic, which could be useful in evaluating cancer predisposition." (PMID 28981467, 2017). "This will create medically important and selective situation whereby cancer cells will be subjected to dual insult of PARP inhibitors and mutations of HR genes including BRCA1/2." (PMID 29214031, 2017). "In particular, BRCA1 and BRCA2 loss of function have been shown to lead to dysfunctional HR in cancer cells whereas the association between PTEN loss of function and dysfunctional HR is more controversial." (PMID 28002809, 2017). "Here, we used a combination of molecular imaging and biochemical tools to study the properties of the BRCA1 in human cancer cells." (PMID 28262780, 2017). "Depletion of EEPD1 also reduced fork restart albeit to a lesser degree than RAD52 depletion in the BRCA1-/- cancer cells." (PMID 29145865, 2017). "Another study showed that Aurora-A and BRCA1/2 inversely controlled the sensitivity of cancer cells to radiotherapy through the ATM/Chk2-mediated DNA repair networks." (PMID 28404933, 2017). "The main objective of this study was to determine the mutational spectrum in BRCA1 and BRCA2 genes in Colombia, and compare two diagnostic strategies to detect patients at high risk of developing cancer and establish prevention programs." (PMID 29021639, 2017). "In cancer tissues, there was huge inter-tumoral heterogeneity of patterns of cytoplasmic and nuclear BRCA1 staining that ranged from strong positivity to complete absence of staining." (PMID 28863181, 2017). "Unfortunately, germline mutations in BRCA1 and BRCA2 can explain high cancer risk only in a fraction (~20%) of the BC families." (PMID 28649653, 2017). "As predicted, BRCA1/2-mutant cancers had improved response (80% vs. 10%) and PFS compared to LOH low subgroup (hazard ratio (HR) 0.27, p < 0.0001)." (PMID 28829366, 2017). "PRL has been recently proposed to impair the tumor-suppressive function of BRCA1 by downregulating expression of the cell cycle inhibitor p21 in cancer cell lines." (PMID 28966800, 2017). "In an early study of women with a BRCA1 or BRCA2 mutation, 33 biopsies revealed seven cancers (21.2%)." (PMID 28265306, 2017). "BRCA1-KO fibroblasts were cultured for 3 weeks with cancer exosomes and exosomes isolated from healthy patients." (PMID 28854931, 2017). "In BRCA1 mutant cancer cells, unrepaired replication forks can generate chromosomal fusions, leading to chromosomal instability and mitotic catastrophe." (PMID 29145865, 2017). "The identification of BRCA1 and BRCA2 (BRCA1/2) genes has greatly enhanced our knowledge of the DNA repair pathways involved in cancer progression and has led to the exploitation of the concept of synthetic lethality in cancer therapy." (PMID 28454085, 2017). "This is because the BRCA-1/2 genes, when mutated, induces a defect in homologous recombination, and pairing this with PARP inhibition allow synthetic lethality of cancer cells." (PMID 28008141, 2017). "Since BRCA1/2 mutant cancer cells use RAD52 as an escape pathway for HR-mediated replication fork repair and restart, depleting RAD52 causes mitotic catastrophe and synthetic lethality in these cells." (PMID 29145865, 2017). "FANCF interacts with BRCA1 and other proteins to initiate other cellular responses in the cancer cells." (PMID 28993682, 2017). "Mass spectrometry analyses of proteins from cancer exosomes and the BRCA1-KO fibroblasts’ membrane were performed to investigate possible de novo expression of molecules involved in vesicles uptake." (PMID 28854931, 2017). "Last but not least, we provide an example on the applicability of an Arabidopsis thaliana—based plant system monitoring the role of cancer-related DNA repair genes BRCA1, BARD1 and PARP1 in processing DNA lesions." (PMID 28587301, 2017).
cancer (continued). "Despite these limitations, this new tool provides a novel means to measure physicians’ assessment of the expected benefits and drawbacks of BRCA1/2 genetic cancer testing." (PMID 28570656, 2017). "Germline mutations affecting a single copy of the HR factors BRCA1 and BRCA2 predispose individuals to cancers of the breast, ovary, prostate, and pancreas." (PMID 28835508, 2017). "Mutations in BRCA1 and BRCA2 render a cancer cell hypersensitive to PARP inhibitors but they can acquire resistance and relapse." (PMID 28714471, 2017). "Genetic testing for BRCA1 and BRCA2 has led to the accurate identification of individuals at higher risk of cancer and the development of new therapies." (PMID 28222693, 2017). "Many other cancer-related genes show distinct alternative splicing profiles in cancers, including BRCA1, BRCA2, MDM2, KLK3 (also named prostate-specific antigen, PSA), and fibroblast growth factor receptors (FGFRs)." (PMID 28257090, 2017). "Carcinomas that exhibit reduced expression of BRCA1 are typically poorly differentiated with high proliferative rate, and inversely correlated with histologic grade." (PMID 28945747, 2017). "All carcinomas that showed methylation of the promoter of BRCA1 had a high‐grade serous histology (n = 9 patients)." (PMID 27767231, 2017). "83.3% (n=10) of the primary carcinomas, vs. 16.7 % (n=2) of the paired recurrent tumors showed hypermethylation of the BRCA1 promoter." (PMID 29137324, 2017). "BRCA1 and 2 highest expression levels were verified in the complex carcinomas samples and in complex adenoma exclusively for BRCA2." (PMID 28945747, 2017). "The inability of the BRCA1-KO fibroblasts to fully differentiate in all cancer phenotypes is a limitation of our study." (PMID 27179759, 2016). "Niraparib was assessed in a Phase I study; it demonstrated responses in 8/20 (40%) ovarian and 2/4 (50%) breast BRCA1/2-related cancers." (PMID 27555886, 2016). "Although sex and organ-specific penetrance of BRCA1-related cancers remains poorly understood, ovarian hormones have been implicated in early cell transformation events." (PMID 27246982, 2016). "Our present results support the tumor-suppressor function of miR-342 observed in other cancers, since overexpression of this miRNA induced apoptosis in a BRCA1-mutant TNBC model." (PMID 26919240, 2016). "In addition, germline variants that predispose to cancer may provide prognostic value and inform on treatment options, as we demonstrated in one of our cases (P0013) with the identification of a BRCA1 germline mutation that led to our recommendation for cisplatin chemotherapy." (PMID 27245685, 2016). "While BRCA1/2-related cancers have been studied with a high level of comprehension, the available information on clinical behavior of novel categories of hereditary breast cancer remains very limited." (PMID 27555886, 2016). "The BRCA1-KO fibroblasts were exposed to cancer patients’ sera or healthy patients’ sera for 2 weeks." (PMID 27179759, 2016). "Histological analysis of tumors generated by BRCA1-KO fibroblasts showed that they were carcinomas with phenotypical characteristics related to the cancers of the blood donor patients." (PMID 27179759, 2016). "Independently of the cancer serum used, all mice injected with cancer sera-treated BRCA1-KO fibroblasts developed visible tumors as early as one week following inoculation." (PMID 27179759, 2016).
cancer (continued). "Overall, our analyses proved optimal for developing new structural oncology applications involving patient-derived cancer cells, while expanding our knowledge of BRCA1’s role in gene regulatory events." (PMID 27583302, 2016). "From this dataset, we investigated the occurrence of TH, we compared the characteristics and features of BC and OC in TH and single BRCA1 or BRCA2 mutations, and we examined LOH in as many cancer samples as possible." (PMID 27836010, 2016). "The peptide enhanced BRCA1-IRIS degradation in cancer cells, suggesting that free BRCA1-IRIS is unstable." (PMID 27489859, 2016). "BRCA1-KO fibroblasts treated with cancer patients’ sera displayed higher proliferation and underwent malignant transformation as opposed to wild type control fibroblasts, which were not affected by exposure to cancer patients’ sera." (PMID 27179759, 2016). "PARP inhibitors were shown to increase DNA damage sensitivity of BRCA1 mutant cancer cells, which appears to be driven by NHEJ activation rather than BER inhibition." (PMID 26424850, 2016). "The age distributions are consistent with existing data that BRCA1 and BRCA2 mutation carriers tend to suffer cancer at earlier age." (PMID 27148484, 2016). "Several studies reported on possible interactions between BRCA1/2 and the telomere-telomerase system in cancer cells." (PMID 26515461, 2016). "Taking BRCA1 as an example, the expression plot shows relatively higher expression in ten cancers compared to matched normal tissues (all adjusted P-values <0.05; Student's t-test)." (PMID 26590405, 2016). "Other studies provided an important role for mammographic textures such as fractal dimensions, GLCM matrix parameters, and power Fourier spectrum in distinguishing between BRCA1/BRCA2 gene mutations and cancer risks." (PMID 27923387, 2016). "This also points out the ability of PB to sensitize BRCA1-defective cancer cells to DNA damaging drugs or radiation." (PMID 27220670, 2016). "Further work is needed to demonstrate the efficacy of RAD52 inhibitors in killing BRCA1- and BRCA2-deficient cancer cells in vivo." (PMID 27649245, 2016). "Especially, when there are defects in DSB repair by mutation of BRCA1/2, inhibition of PARP1 results in un-repairable DNA DSBs and apoptosis of cancer cells." (PMID 27643881, 2016). "Here we use tunable materials to facilitate the three-dimensional (3D) analysis of BRCA1 gene regulatory complexes derived from human cancer cells." (PMID 27583302, 2016). "Prior work has demonstrated a number of genes specifically upregulated in BLBC, although the mechanism of the BLBC phenotype in BRCA1-mutant cancer is yet to be defined." (PMID 27708239, 2016). "Poly (adenosine diphosphate-ribose) polymerase (PARP) enzymes are critical to cell proliferation and are differentially upregulated in many cancers including TNBC and BRCA1/2-associated tumors." (PMID 27977696, 2016). "As expected, cancer tissues showed significantly higher levels of BRCA1 promoter methylation (mean 32.6%; median 31.9%) than the adjacent normal samples (mean 16.2%; median 13.0%) (P < 0.0001)." (PMID 27027444, 2016). "For example, pioneering studies of SL partners in BRCA1 and BRCA2-deficient cancer cells identified PARP1 as a promising drug target." (PMID 27655641, 2016). "Presymptomatic salpingo-oophorectomy and mastectomy for female BRCA1 and BRCA2 mutation carriers after child-bearing age can significantly reduce morbidity and mortality of these two cancers." (PMID 26867194, 2016). "Here, reconstitution of wild type BRCA1 plasmid in both MX1 and HCC1937 showed selective cytotoxic activity of PB against BRCA1 mutated cancer cells." (PMID 27220670, 2016). "Rucaparib induces synthetic lethality in cancer cells defective in the homologous recombination repair pathway including BRCA-1/2." (PMID 27002934, 2016). "Of the 73 TNBC from BRCA1 carriers, 3 (4.1%) expressed both, with one cancer having weak AR staining (1–10% cells) and 2 having >10% AR staining." (PMID 28721372, 2016).
cancer (continued). "Overexpression of UHRF1 occurs in many types of cancer, and aberrantly expressed UHRF1 causes cancer cell activation through hyper-methylation of tumor-suppressor genes such as BRCA1, CDKN2A, p73, and RASSF1." (PMID 27072587, 2016). "These genes participate either in DNA repair and checkpoint control, apoptosis or in the regulation of cell proliferation, adding other crucial targets for cancer progression besides BRCA1 and BRCA2 dependent DNA repair." (PMID 26979459, 2016). "6-OH-dopa inhibited RAD52 foci formation in response to DNA damage in murine hematopoietic cells deficient in BRCA1 and selectively killed BRCA1 and BRCA2-deficient human cancer cells." (PMID 27649245, 2016). "Higher proliferative rates caused by the hormone signaling in these cells would therefore explain the sex and organ-specific penetrance of BRCA1-related cancers." (PMID 27246982, 2016). "Effectors of HR such as BRCA1 (Breast Cancer 1), BRCA2, MRE11A and RAD51 were significantly expressed following IR." (PMID 27495836, 2016). "The exposure of BRCA1-KO fibroblasts has added value to the genometastatic theory since we have observed a full differentiation into at least two cancer cell lineages (colon and pancreas)." (PMID 27179759, 2016). "While disease-associated mutations in RAD51 are extremely rare, depletion by siRNA or miRNA induces a “BRCAness” phenotype and sensitizes cancer cells to DNA damaging agents such as cisplatin and PARP1 inhibitors similarly, to BRCA1 and BRCA2 mutations." (PMID 26910887, 2016). "Given the well-established BC risks for BRCA1 and BRCA2 mutations, a multiplicative model would imply very high cancer risk at young ages." (PMID 27836010, 2016). "Women carrying a pathogenic germline mutation in the BRCA1 and BRCA2 genes have an increased lifetime risk of developing breast, ovarian, and several other cancers." (PMID 27553291, 2016). "In our study, we documented, for the first time, a significant increased uptake of cancer-derived exosomes by BRCA1-KO fibroblasts and HEK293 cells when compared to wild type fibroblasts." (PMID 27179759, 2016). "42% reported more than 10 of their patients having had genetic testing for cancer, the majority for BRCA1/2." (PMID 27980798, 2016). "HCC1937/wt BRCA1 cells showed the presence of a distinct CD44high/24–population (3.07 ± 1.12 %) within its CD44+/24–/low (30.6 ± 5.0 %) putative cancer stem cell population." (PMID 27229859, 2016). "To further assess how BRCA1 influences cancer stemness, we compared and contrasted between the EMT and stem cell marker expression patterns in HCC1937 and HCC1937/wt BRCA1." (PMID 27229859, 2016). "The present study intends to evaluate how the BRCA1 defect augments PB to selectively kill these cancer cells." (PMID 27220670, 2016). "For example, exogenous ligands of Ahr inhibit BRCA1 oncogene to suppress cancer, whereas, the endogenous ligands exhibit opposing effects." (PMID 27907195, 2016). "Expression of breast cancer 1 (BRCA1), breast cancer 2 (BRCA2), cathepsin D (CTSD), BCL2, and WISP2 were significantly increased." (PMID 27379522, 2016). "Associations between BRCA1, MCM1, and CDKN3 as the other three potential targets of miR-146a-5p and tumorigenesis were already reported for other cancers." (PMID 26859141, 2016). "Specifically, three of the 17 cancer driver TFs were found to be over-represented (as predicted binding sites: BRCA1, CBFP and EP300; Fisher’s test p values < 0.05)." (PMID 27553366, 2016). "Previously, many alternative splicing variants had been observed in cancer, for examples, EGFR, CD44, NER and BRCA1." (PMID 27557076, 2016). "Mutations in cis-acting splicing elements were shown in both oncogenes (KIT, CDH17, and BRCA1/2) and tumor suppressors (LKB1 and KLF6), which have causal role in cancer initiation and progression." (PMID 28105922, 2016). "Among the studied samples, 45% of cancer tissues and 35% of normal tissues had combined BRCA1 and 17βHSD-1 promoter methylation." (PMID 27413552, 2016).
cancer (continued). "From the current understanding of the biological functions of BRCA-mutant cancer, there appears to be a link between the BRCA1 pathway and BLBC." (PMID 27977696, 2016). "Detailed personal and family history of cancer was reported for 31 BRCA1 and 25 BRCA2 patients from those with available records." (PMID 27069714, 2016). "BRCA1 and BRCA2 are critical for the process of DNA repair by homologous recombination repair (HRR), and deficient HRR makes cancers more susceptible to DNA-damaging agents." (PMID 27959926, 2016). "By making use of protein-protein interaction information, we suggested eight cancer drugs that target genes upstream of BRCA1." (PMID 27801815, 2016). "BRCA1 (breast cancer 1) performs DNA repair functions and it is normally expressed in breast tissue." (PMID 27801815, 2016). "The information provided was expected to be fairly similar to that provided by the cancer geneticist at the time of BRCA1/2 testing, and the up‐to‐date information about the genetic counselling services available in France was not thought to be actionable." (PMID 26205609, 2016). "Multiple studies indicate that BRCA1/2-driven OC are characterized by increased sensitivity to platinating agents as compared to sporadic carcinomas." (PMID 27555886, 2016). "In Canada, all genetic testing for BRCA1 and BRCA2 must be ordered by a cancer genetics professional associated with a cancer medical genetics clinic, where clinics are managed by provincial health care jurisdictions." (PMID 25884701, 2015). "Clinical examples that take advantage of defective DNA repair in cancer therapy include single and combination treatment of germline BRCA1/2 ovarian, breast and prostate cancers with PARP inhibitors." (PMID 25868852, 2015). "In six patients, they identify LoF PPVs in four dominant cancer-associated genes (CHEK2, ATM, RAD50, and CDKN2B), in addition to original clinically diagnosed BRCA1/2 mutations." (PMID 26137530, 2015). "Our results reveal a novel regulatory model of mitochondrial fission that affects cisplatin sensitivity via miRNA and BRCA1 in cancer cells." (PMID 25912308, 2015). "An opposite association for CD99 was observed with sporadic basal cancers showing increased expression compared to BRCA1 cancers (p = 0.024)." (PMID 26152113, 2015). "Noteworthy, PARP inhibitors, the first molecularly targeted anti-cancer drugs that exploit the DNA repair defect present in BRCA1- or BRCA2-mutant cancers were FDA-approved at the end of 2014." (PMID 26734064, 2015). "One additional study suggests that alternating imagining is a more cost efficient strategy, especially for BRCA1 carriers, largely related to the high incidence of cancer." (PMID 25741458, 2015). "BRCA1 and BRCA2 (breast cancer susceptibility genes 1 and 2) genes encode for tumour suppressor proteins important in DNA repair pathways." (PMID 26056364, 2015). "Some studies have reported that miRNAs can impact sensitivity to cancer therapy by targeting BRCA1/2." (PMID 25537514, 2015). "All previously known BRCA1 and BRCA2 variants in the specimens were successfully detected by both platforms and in all 3 validation runs (i.e., 100% accuracy for cancer-associated mutations)." (PMID 26295337, 2015). "The complex role of BRCA1 in cellular homeostasis has made elucidating its key functions in cancer difficult." (PMID 26379698, 2015). "For example, while endogenous ligands enhance cancer by transcription of BRCA1 oncogene, activation of Ahr by exogenous agonists suppress BRCA1 gene expression." (PMID 26377202, 2015).